STAT3 (signal transducer and activator of transcription 3)
Diseases named in the same sentence as STAT3 in open-access papers (continued):
Sharing a sentence is not in itself a finding about the gene and the disease.
colorectal cancer (continued). "The downregulation of CD44 after treatment with GO-Y031 suggests that curcumin analogs inhibit gastric cancer stem cells and reflect the inhibition of STAT3 and/or CD44 in colorectal cancer stem cells." (PMID 25331984, 2015). "In fibrosarcoma and colorectal cancer cells, the mitogen-activated protein kinase (MAPK) signaling pathway inhibited the expression of VEGF, bFGF and STAT3, and the p38 MAPK signaling pathway mediated VEGF expression in bone marrow mesenchymal stem cells." (PMID 24944688, 2014). "STAT3 has been shown to directly bind the gene promoter for p21WAF1/CIP1 inducing its expression in multiple cell types including epidermoid carcinoma, colorectal carcinoma, and bone osteosarcoma cells." (PMID 24743777, 2014). "illustrated the biological significance of JAK2/STAT3 signaling for colorectal cancer apoptosis and provided novel evidence that the inhibition of JAK2/STAT3 induced apoptosis via the mitochondrial apoptotic pathway." (PMID 23483946, 2013). "Despite these advances, the role of PTEN, STAT3 and VEGF-C in colorectal cancer has yet to be reported." (PMID 23170117, 2012). "In conclusion, PTEN, STAT3 and VEGF-C are prognostic factors in colorectal cancer and VEGF-C can be used as an independent prognostic factor." (PMID 23170117, 2012). "In the present study, we examined PTEN, STAT3 and VEGF-C protein expression in colorectal cancer and analyzed their prognostic ability." (PMID 23170117, 2012). "This study was designed to identify the correlation between PTEN, STAT3 and VEGF-C expression and prognostic ability in colorectal cancer." (PMID 23170117, 2012). "Future research should focus on the methods by which to alter expression of PTEN, STAT3 and VEGF-C in order to provide new targets for clinical treatment, and to improve survival and quality of life of colorectal cancer patients." (PMID 23170117, 2012). "The expression rates of PTEN, STAT3 and VEGF-C were 32.4, 60.3 and 63.2% in colorectal cancer samples, and 90.0, 0 and 0% in normal tissues, respectively; these differences were significant (p<0.05)." (PMID 23170117, 2012). "PTEN, STAT3 and VEGF-C expression was detected in 32.4, 60.3 and 63.2% of colorectal carcinoma cases and 90.0, 0 and 0% of normal colon samples, respectively." (PMID 23170117, 2012). "In colorectal carcinoma, PTEN and STAT3 protein expression was significantly negatively correlated (r=−0.402, p=0.001) as was PTEN and VEGF-C protein expression (r=−0.320, p=0.008)." (PMID 23170117, 2012). "Curcumin also inhibited STAT3 phosphorylation (Y705) in the ALDH+/CD133+ subpopulations of SW480 and HCT-116 colorectal cancer cell lines at higher concentration (50 μM)." (PMID 21694723, 2011). "The SAM programme typed the following genes to be statistically significant in the compared groups as genes differentiating stage I and II of clinical progression of colorectal cancer: AKT1, STAT3, MCL1, and STAT5B." (PMID 22363883, 2011). "We next examined the effect of FLLL32 on STAT3 DNA binding activity in U87 glioblastoma, U266 multiple myeloma and SW480 colorectal cancer cells." (PMID 20712901, 2010). "In colorectal cancer (CRC), STAT3 activation serves as a key indicator of unfavorable outcomes." (PMID 42194100, 2026). "Furthermore, IL-21 signalling was found to promote the proliferation and migration of colorectal cancer cells by suppressing the activation and phosphorylation of ERK1/2 and STAT3." (PMID 41957653, 2026). "The COLO320 line was chosen as it is also one of the few available colorectal cancer cell lines via ATCC that is derived from a female patient and positive for the prolactin receptor, allowing us to explore the phosphorylation of STAT3 in response to prolactin treatment." (PMID 41501898, 2026). "Overexpression of STAT3 promoted CXCL8 production and NETs formation in colorectal cancer patients." (PMID 41019086, 2025).
colorectal cancer (continued). "Similarly, in the colorectal cancer microenvironment, ANGPTL4 overexpression in endothelial cells activated JAK2/STAT3 signaling, enhancing angiogenesis and metastasis." (PMID 40616161, 2025). "More and more evidences demonstrated that the expression of p-STAT3 in CAF is negatively correlated with the prognosis in colorectal cancer, and the persistent activation of STAT3 in CAF promotes the tumor growth and drug resistance in colorectal cancer." (PMID 40703348, 2025). "The upregulation of lncRNA ITIH4-AS1 in colorectal cancer enhances RE1 silencing transcription factor (REST) downregulation or depletion, which consequently upregulates ITIH4-AS1 and promotes tumor proliferation and metastasis through JAK/STAT3 pathway." (PMID 39136000, 2024). "After succinate treatment, the colorectal cancer cell lines SW480 and HCT116 had enhanced migration and invasion, the expression of biomarkers of EMT was promoted, and significantly increased phosphorylation of STAT3." (PMID 38486162, 2024). "Additionally, inhibitors of STAT3, COX-2, and PDE5 have been tested to reduce MDSC immunosuppressive activity, showing potential in cancers, such as melanoma and colorectal cancer." (PMID 39513886, 2024). "Furthermore, another study found that during RT, the JAK2/STAT3 signaling pathway was activated, which in turn activated downstream CCND2 expression and enhanced CSCs properties, leading to radioresistance in colorectal cancer." (PMID 38355684, 2024). "Additionally, the effects of UA on inhibiting the nuclear translocation of STAT3 in colorectal cancer cells were assessed, and it was found that in HCT116 and HT29 cells, UA substantially decreased the expression of JAK2 and STAT3." (PMID 38397437, 2024). "c-RAF’s role in promoting STAT3 activation has also been associated in PDAC and colorectal cancer as being pro-oncogenic, irrespective of c-RAF kinase activity." (PMID 38637546, 2024). "In addition to STAT3, HIF-1α can promote the expression of NF-κB to induce colorectal cancer invasion." (PMID 39014491, 2024). "In this study, we have demonstrated that exosomal miR-320d derived from colorectal cancer cells enhances angiogenesis in vascular endothelial cells and promotes cancer cell metastasis by downregulating GNAI1 expression, enhancing JAK2/STAT3 protein phosphorylation, and increasing VEGFA expression." (PMID 39695099, 2024). "STAT3 and KRAS were significantly down-regulated in colorectal cancer." (PMID 39830506, 2024). "STAT3 is an important transcription factor in the JAK/STAT3 pathway, and an increase in STAT3 phosphorylation can increase its activity and promote the proliferation of colorectal cancer cells." (PMID 37024465, 2023). "Since CMTR1 knockdown reduced STAT3 expression and activation, we further examined whether CMTR1 knockdown can enhance the efficacy of PD1 blockade immunotherapy in colorectal cancer by activating tumor cell-intrinsic type 1 IFN signaling." (PMID 37024465, 2023). "The role of FOXQ1 in immunology has been preliminarily confirmed, with previous research showing that cancer-related macrophages induce epithelial–mesenchymal transition by regulating the JAK2/STAT3/miR-506-3p/FOXQ1 axis, thereby enhancing the invasion and migration of colorectal cancer cells." (PMID 36118871, 2022). "Using molecular docking, a study to find possible applicable curcumin targets for treating colorectal cancer showed that curcumin could stably combine with EGFR, STAT3, and AKT1." (PMID 36297027, 2022). "Furthermore, the TIC phenotype in colorectal cancer can be regulated by an extracellular insulin-like growth factor (IGF) signaling pathway, which regulates NANOG via STAT3 phosphorylation." (PMID 36118530, 2022).
colorectal cancer (continued). "For example, piRNA‐54265 can bind to the PIWIL2 protein and promote the formation of the PIWIL2/STAT3/phosphorylated SRC (p‐SRC) complex, activating STAT3 signalling and promoting the proliferation, metastasis and chemotherapy resistance of colorectal cancer cells." (PMID 33942984, 2021). "From the figure, it is apparent that the JAK/STAT3, the PI3K/AKT/mTOR, and the RAS/RAF/ERK pathways are highly up-regulated and are possibly the main reason for an out of control cell proliferation in colorectal cancer." (PMID 33596259, 2021). "In colorectal cancer, circSPARC not only regulates the expression of JAK2 through the ceRNA mechanism to affect the activation of STAT3 but also enhances the nuclear translocation of p-STAT3 through the recruitment of FUS RNA binding protein." (PMID 34425834, 2021). "In addition, KIF20A knockout reduces colorectal cancer cell proliferation and migration by inhibiting the JAK/STAT3 pathway." (PMID 34025420, 2021). "For instance, piRNA-54265 binds with the PIWIL2 protein and promotes the formation of the PIWIL2/STAT3/phosphorylated-SRC (p-SRC) complex, which activates STAT3 signaling and promotes the proliferation, metastasis, and chemo-resistance of colorectal cancer cells." (PMID 33802524, 2021). "Although LPA is known to elicit cellular responses through various signaling pathways, ROCK, STAT3, p38 MAPK, and PI3K/AKT pathways are specifically involved in LPA-induced proliferation in various cell types, such as corneal endothelial cells, colorectal cancer cells, and renal mesangial cells." (PMID 34639115, 2021). "For instance, Polo‐like kinase 3 (PLK3) could inhibit glucose metabolism by targeting HSP90/STAT3/HK2 signalling, indicating it may serve as a potential therapeutic target in colorectal cancer." (PMID 34423480, 2021). "RES inhibits STAT3 Tyr705 phosphorylation in ovarian cancer, pancreatic cancer, head and neck tumor, osteosarcoma, colorectal cancer, colon cancer, and STAT3S727 phosphorylation in head and neck tumor and colorectal cancer." (PMID 33040485, 2020). "Secondly, we demonstrated that IL-10 produced by M2-TAMs induced EMT in colorectal cancer cells and that Cer and PA blocked this process by inhibition of IL-10 expression and the EMT-related signaling molecules STAT3, Snail, and NF-κB in colorectal cancer cells." (PMID 32222879, 2020). "STAT3 signaling inhibition plays a critical role in the RES‐induced suppression of several cancer types, including ovarian cancer, pancreatic cancer, head and neck tumor, osteosarcoma, colorectal cancer, and colon cancer." (PMID 33040485, 2020). "Similarly, Rac1 is overexpressed in colorectal cancer (CRC), where Rac1 is shown to co-immunoprecipitate with STAT3 in HCT116 CRC cells." (PMID 32915198, 2020). "Further, IFITM2 was significantly up-regulated and induced after activation of beta-catenin signaling in colorectal cancers, and it was also reported to promote gastric cancer growth and metastasis through the insulin-like growth factor (IGF1)/IGF1 receptor (IGF1R)/STAT3 signaling pathway." (PMID 32765489, 2020). "We further demonstrated that the targeting of HSPA5 by HA15 significantly inhibited cell viability and increased apoptosis and prevented the formation of colorectal cancer HT29-derived tumorspheres, thus indicating that the STAT3-miR-30a-HSPA5 axis contributed to anti-apoptosis in CRC." (PMID 33023006, 2020).
colorectal cancer (continued). "Studies showed that BDL301 could significantly inhibit cell growth and induced apoptosis in colorectal cancer CT-26 and HCT-116 cells in vitro and markedly suppress the growth of CT-26 tumors in vivo via inhibiting STAT3 signaling pathway." (PMID 31354479, 2019). "Our data suggest that compound 19 can be an efficient therapy for cancer stem cells by inhibiting STAT3 and repressing non-canonical function of telomerase for stemness in colorectal cancer." (PMID 31360301, 2019). "In colorectal cancer cells, CTS inhibited proliferation and growth via STAT3 signaling as well." (PMID 31780948, 2019). "Collectively, these results suggested that PIPKIγ may activate the PI3K-Akt-STAT3 signaling pathway, which can further increase CCL2 levels in colorectal cancer." (PMID 31781676, 2019). "This study suggests that PLK3 inhibits glucose metabolism by targeting HSP90/STAT3/HK2 signaling and PLK3 may serve as a potential therapeutic target in colorectal cancer." (PMID 31655629, 2019). "NCK1 is adaptor protein that is downstream of receptor tyrosine kinase and STAT3 signaling; both NCK1 and the other correlated gene, SLC35G2, may be involved in colorectal cancer pathogenesis." (PMID 30767760, 2019). "In summary, our data indicates a connection between STAT3 and IRF9 in colorectal cancer." (PMID 30679726, 2019). "Our findings provide insight into the important role of SIRT2 in colon tumour angiogenesis and suggest that SIRT2/STAT3/VEGFA might be a novel prognostic biomarker and a potential therapeutic target for patients with colorectal cancer." (PMID 30584257, 2018). "Specifically, miR-9, miR-17, miR-19a/b, miR-20a/b, miR-21, miR-155 and miR-181 have been identified as miRNAs involved in STAT3-dependent circuits within various cancers, although not specifically colorectal cancer." (PMID 30603058, 2018). "In conclusion, microRNA-375 might function as a tumor-repressive gene to inhibit cell proliferation, mainly through targeting both JAK2/STAT3 and MAP3K8/ERK signaling pathways in colorectal cancer." (PMID 28186962, 2017). "Thus, our study indicates that high IL-35 levels in colorectal cancer promotes the increased production of IL-35 via STAT1 and STAT3 and results in the suppression of T cell proliferation, leading to tumor immunotolerance." (PMID 27682874, 2016). "Most importantly, we showed the relevance of these findings to clinical patient samples and demonstrated that phosphorylation at S727 of STAT3 and expression of Col XVII could serve as two prognostic factors in colorectal cancer patients." (PMID 27306323, 2016). "Thus, our study indicates that the high level of IL-35 observed in colorectal cancers promotes its own production via STAT1 and STAT3 to suppress T cell proliferation during tumor immunity." (PMID 27682874, 2016). "In conclusion, we have identified PRSS8 as a tumor suppressor in colorectal cancer formation and progression, and PRSS8 might be one of the key elements that suppress Sphk1/S1p/Stat3/Akt inflammatory signaling during colorectal carcinogenesis." (PMID 27050145, 2016). "Additionally, an IL-6/STAT3/miR34a feedback loop has been shown to promote EMT-mediated cancer invasion and metastasis in human colorectal cancer cells." (PMID 25638155, 2015). "A STAT3-decoy oligonucleotide (ODN) can trap an activated STAT3 dimer in the cytoplasm by inhibiting interaction between active STAT3 and importin, resulting in increased apoptosis in colorectal cancer cells." (PMID 24743778, 2014). "Kaplan-Meier single factor survival analysis and the log-rank test indicated that the 3- and 5-year survival rates of STAT3 protein-positive colorectal cancer patients were significantly lower than STAT3 protein-negative patients (p=0.005)." (PMID 23170117, 2012). "Combined detection of PTEN, STAT3 and VEGF-C expression may provide an index with which to determine the degree of malignancy, metastasis and prognosis in colorectal cancer and guide clinical treatment." (PMID 23170117, 2012).
colorectal cancer (continued). "In conclusion, this study indicates that PTEN, STAT3 and VEGF-C expression are beneficial prognostic factors, which may aid in the accurate assessment of prognosis and guide clinical treatment of colorectal cancer patients." (PMID 23170117, 2012). "To date, there are no reports available on the role of Jak-STAT3 signaling pathway in bufalin-induced apoptosis in colorectal cancer cells." (PMID 23110625, 2012). "Ogunwobi and Beatles prove in their studies of leptin effect on colorectal cancer cells that leptin stimulates proliferation and inhibits apoptosis in human colorectal cancer cells, involving in those processes not only PI3 kinase but also JAK2 kinase and a transcription factor, the STAT3 protein." (PMID 22363883, 2011). "Similarly, in colorectal cancer, PDPN+ CAFs secrete CCL2 to establish a PDPN/CCL2/STAT3 autocrine feedback loop that maintains CAFs heterogeneity and, via paracrine signaling, activates STAT3 in ECs to drive angiogenesis." (PMID 41514658, 2025). "In cells such AS colorectal cancer and non-small cell lung cancer, AS-IV can dose-dependently enhance the Bax/Bcl-2 ratio and activate caspase-3, and simultaneously downregulate Mcl-1 and NF-κB by blocking the IL-6/JAK2/STAT3 axis, thereby inhibiting anti-apoptotic signals." (PMID 40949137, 2025). "This study demonstrated that UA could effectively inhibit CRC proliferation by inducing ferroptosis via regulation of system xc- subunits and miR-214-3p/Stat3/GPX4 axis, suggesting UA could serve as a promising anti-colorectal cancer candidate requiring further validation and optimization." (PMID 41341590, 2025). "Additionally, miR-708 enhances STAT3 activation by targeting the 3’UTR of SOCS3, and the decreased expression of MEG3 in colorectal cancer (CRC) tissues and cells leads to a reduction in SOCS3 levels, promoting the malignant proliferation of colon stem cells and CRC cell lines." (PMID 39830506, 2024). "Through the validation of differential gene expression in the GEPIA database, we found that the validation of MYC and STAT3 in the GEPIA database yielded the same results as the GEO database, which could be able to serve as targets to play a role as tumor marker in colorectal cancer." (PMID 39830506, 2024). "Moreover, in colorectal cancer, miR-150-5p inhibits tumor progression by targeting VEGFA; members of the STAT proteins, STAT1, STAT3, and STAT5, have been attested as regulators mediating the expression of VEGFA, involving the mechanisms of angiogenesis as well." (PMID 38737443, 2024). "A previous report showed that IL-6/STAT3 inflammatory signaling axis induces the deacetylation of FOSL1 at the Lys-116 residue located within its DNA binding domain, leading to the increase of FOSL1 transcriptional activity and acquisition of colorectal cancer (CRC) stem-like properties (stemness)." (PMID 37642779, 2023). "Therefore, the combination of inhibiting p-STAT3 and METTL3 simultaneously may shed new sight on colorectal cancer therapy." (PMID 38001065, 2023). "At present, it is generally believed that the activity of STAT3 mainly depends on the homodimerization of STAT3 and the activation of gene transcription, which regulates the proliferation, apoptosis, invasion and metastasis, angiogenesis and immune status in TME of colorectal cancer." (PMID 38273841, 2023). "Interestingly, the co‐transcription between STAT3 and STAT4 has been reported in colorectal carcinoma, but whether STAT4 indirectly transactivates CD274 (coding PD‐L1) through synergistic effect with STAT3 remains unknown." (PMID 38107057, 2023). "Interestingly, a study revealed that Nifuroxazide treatment, a signal transducer and activator of transcription 3 (STAT3) inhibitor, was capable of reducing circulating and tumoral MDSC and exerting pro-apoptotic and anti-metastatic activity in the CT26 colorectal cancer mouse model." (PMID 34072037, 2021).